FTH1 (ferritin heavy chain 1)
Diseases named in the same sentence as FTH1 in open-access papers (continued):
Sharing a sentence is not in itself a finding about the gene and the disease.
infection (42 papers, 2010 to 2025). The state of being infected such as from the introduction of a foreign agent such as serum, vaccine, antigenic substance or organism. "Overall, these data indicate that iron redistribution in response to infection is altered in mice deficient in myeloid FTH1, with a tendency for increased iron in circulation and lower iron accumulation in the liver." (PMID 35008695, 2021). "Overall, in our mouse model of infection, the deficiency in FTH1 in myeloid cells caused an increased resistance against M. avium, related to the restriction of pathogen access to iron." (PMID 35008695, 2021). "Upon infection by the intramacrophagic pathogen M. avium, the alteration in the iron distribution pattern associated with FTH1 deficiency in myeloid cells leads to increased host protection, due to decreased iron availability for bacterial proliferation." (PMID 35008695, 2021). "Finally, we show that mice deficient in FTH1 in myeloid cells are more resistant to infection by M. avium, mainly due to a slower growth of the bacteria." (PMID 35008695, 2021). "Indeed, myeloid fth1-deficient mice had decreased survival and higher bacterial loads in their organs after aerosol infection with Mtb when compared to wild-type controls." (PMID 32325688, 2020). "Cytosolic iron may be bound by Ftl1 and Fth1 encoded ferritin, which are also induced late in infection." (PMID 31848386, 2019). "While BCG stimulation initially increased the expression of longer FTH1 transcript isoforms at 24 hours, this increase diminished by 48 hours post-infection, returning to baseline levels compared with uninfected THP-1 macrophage (lane 1 vs. lane 2)." (PMID 40384984, 2025). "Macrophages upregulate FTH1 expression during infection to sequester iron, thereby depriving pathogens of this essential nutrient and enhancing microbial killing." (PMID 39941157, 2025). "We observed increased co-localization of FTH1 with the lysosomal marker LAMP1 after PRV-GFP infection by using confocal microscopy." (PMID 40891826, 2025). "Fth1−/− mice had lower levels of circulating tumor necrosis factor (TNF)-alpha, interferon-gamma (IFN-gamma) and interleukin (IL)-6 than Fth1+/+ mice, 60 days after infection." (PMID 35008695, 2021). "Again, in normal (Fth1+/+) mice, infection was accompanied by iron accumulation inside granulomas, while most ferroportin staining was found in hepatocytes." (PMID 35008695, 2021). "The total amount of iron per organ followed the same pattern: before infection, Fth1+/+ mice had 195.2 ± 93.95 μg of iron per liver, while Fth1−/− had 80.6 ± 22.27 μg per liver." (PMID 35008695, 2021). "Before infection, Fth1−/− mice had roughly half the concentration of liver iron found in Fth1+/+ mice." (PMID 35008695, 2021). "After infection, total liver iron in Fth1+/+ mice was 108.8 ± 87.21 and in Fth1−/− mice was 80.46 ± 38.49 μg." (PMID 35008695, 2021). "The liver is also the organ where most of the bacteria are found throughout the infection and where the differences in bacterial load between Fth1−/− and Fth1+/+ mice were more pronounced." (PMID 35008695, 2021). "Upon infection, iron concentration in the liver slightly but significantly decreased in both groups, remaining lower in Fth1−/− than in Fth1+/+ mice." (PMID 35008695, 2021). "In this work, we show that FTH1 produced by myeloid cells plays a crucial role in iron redistribution during infection, being essential for iron deposition and storage inside macrophages." (PMID 35008695, 2021). "With infection, serum ferritin was significantly increased in Fth1+/+ mice while a small, but significant, decrease of serum ferritin was observed in Fth1−/− mice." (PMID 35008695, 2021). "On the other hand, FTH1 expression modulates macrophage activation by immune and microbial stimuli and is essential for cell protection against oxidative stress, suggesting that FTH1 contributes to host defense against infection." (PMID 35008695, 2021).
infection (continued). "When Fth1 expression was down-modulated, mice succumbed more rapidly to infection, in a parasite-burden-independent manner." (PMID 32325688, 2020). "Fe-supplementation resulted in a significant down-regulation of HFE3 (TFR2), HAMP, FPN1, and LCN2 while BMP6 and FTH1 were significantly up-regulated, compared to the placebo group, at 4 weeks post-infection." (PMID 31382404, 2019). "Expression of BMP6 and FTH1 were up-regulated by Fe-supplementation at both, 4 and 8 weeks post-infection." (PMID 31382404, 2019). "None of the components of the ferritin iron storage system are affected by infection with Salmonella or Francisella as measured by determining the expression of Fth1 and Ftl1 (p = 0.91 and p = 0.90 for Francisella and p = 0.88 and p = 0.78 for Salmonella)." (PMID 20184753, 2010). "The expression of FTH1 is regulated through multiple pathways in response to infection." (PMID 40384984, 2025). "Interestingly, APR decreased PPRV infection-induced accumulation of intracellular Fe2+ via miR-3955-5p/FTH1 axis and ultimately inhibited reticulophagy and ferroptosis." (PMID 40126010, 2025). "These genes contribute to the regulation of iron metabolism (FTH1), modification of proteins in response to infection (HERC5), presentation of antigens to the immune system (MAMU-AG), control of apoptotic pathways (IFI6 and PLAC8), and direct antiviral activities." (PMID 40742121, 2025). "Although the basal levels of IRP2 and FTH1 were increased in Fam96a-deficient BMDMs compared with the WT control, they failed to increase further after infection." (PMID 38713713, 2024). "After infection with TgCtwh3, the TfR1 responsible for iron intake in the cells is decreased; the bound iron stored in FTH1 and heme is released, respectively, by NCOA4 and HO-1, Additionally, the Fpn responsible for iron exclusion in the cells is downregulated." (PMID 37651502, 2023). "Ferritin heavy chain-1 (FTH1) with iron oxidase activity was downregulated after infection." (PMID 37651502, 2023). "We show that FTH1 in myeloid cells is required for iron retention in response to infection." (PMID 35008695, 2021). "Furthermore, bacterial loads in the liver, spleen, and bone marrow, 60 days after infection, were significantly lower in Fth1−/− as compared to Fth1+/+ mice." (PMID 35008695, 2021). "FTH1 released from macrophages during infection may play an important role in systemic and local iron redistribution." (PMID 35008695, 2021). "However, ferroportin distribution was markedly different between Fth1+/+ and Fth1−/− mice during infection." (PMID 35008695, 2021). "However, upon infection with B. pseudomallei, Fpn mRNA levels were significantly reduced in both iron- and solvent-treated macrophages, whereas Fth1 and HO-1 expression were significantly enhanced by FAC." (PMID 29329289, 2018). "Importantly, we also found that FTH1 produced by myeloid cells in response to infection may be found in circulation and that it plays a key role in iron redistribution." (PMID 35008695, 2021). "Our analysis revealed a significant increase in both mRNA and protein expression of FTH1, FTL, and TFR1 following infection with N. seriolae." (PMID 39717544, 2024). "The higher expression of FTH1, ISG15, SRGN and S100A12 genes observed in infected animals suggests the activation of the host immune system to resist the infection." (PMID 37761803, 2023). "Surprisingly, we found that the increase in serum ferritin observed in Fth1+/+ mice upon infection was due to increases in both FTL and FTH1 chains." (PMID 35008695, 2021). "At 8 weeks post-infection, expression of BMP6, HAMP, FPN1, FTH1, NRF2, and LCN2 was significantly up-regulated, while HFE1 was significantly down-regulated by Fe-supplementation, compared to the placebo group." (PMID 31382404, 2019). "Ferritin (FTH1), the primary intracellular iron storage protein, was sharply upregulated in PBMC of PN piglets, implicating the iron sequestration response to infection." (PMID 30778359, 2018).
infection (continued). "A clear difference in expression of iron regulatory genes was observed with a consistent and significant down-regulation of FTH1, SLC11A1, SLC11A2, HMOX1 and TFRC in animals controlling the infection." (PMID 24505407, 2014). "The infection of BMM with mycobacteria induces TNF-alpha production, a cytokine that (specifically) induces the expression of H-ferritin by an increase in Fth1 transcription." (PMID 24349383, 2013). "The siRNAs targeting the longer FTH1 isoform (FTH1-L) or total FTH1 transcripts were transfected into THP-1 macrophages 24 hours prior to Mtb infection, and FTH1 mRNA levels and protein abundance were assessed at 24- and 48-hours post-infection." (PMID 40384984, 2025). "Although SLC7A11 and FTH1 expression also increased at 1 h post-infection, this increase was not significant." (PMID 41413615, 2025). "Repeated administration of FAC resulted in slightly elevated gene expression of Hamp and Fth1, and reduced mRNA levels of Fpn 48 hours after infection, although results were not statistically significant." (PMID 29329289, 2018). "Ferritin heavy chain 1 (FTH1), ferritin light chain (FTL), mitochondrial ferritin (FTMT), and ATP6V1F were the downregulated genes identified in A. baumannii without resistant gene infection-associated pulmonary host response." (PMID 39857726, 2025). "Mice lacking ferritin heavy chain (FTH1) in myeloid cells suffer worsened Salmonella infection." (PMID 38798412, 2024). "For ferroptosis, the significantly up-regulated proteins shared by the L. monocytogenes 10403s and M7 infection groups were Acsl5, Tf, Acsl1, Tfrc, and Lpcat3, and the significantly down-regulated proteins were Fth1 and Ftl1: neither changed significantly in the comparison group." (PMID 35682909, 2022). "Moreover, during infection in the presence of albumin, C. glabrata drastically changed the expression of genes involved in iron uptake (FTR1 and SIT1), intracellular iron distribution and consumption (FTH1, HMX1) and virulence (EPA1, YPS2, AUS1)." (PMID 34710198, 2021). "In accordance, TLR-2-/- BMM did not increase Fth1 mRNA expression upon infection." (PMID 24349383, 2013). "Furthermore, the higher expression of chemokine (CXC motif) receptor 2 (Cxcr2), Fc gamma receptor III [Fcgr3 (Cd16)], and ferritin heavy chain (Fth1) in clusters 0, 1, 2, 4, and 5 indicated the presence of migrating and maturing neutrophils, regardless of infection status." (PMID 38767331, 2024).
iron metabolism disorder (5 papers, 2021 to 2025). "On the other hand, FTH1 regulates intracellular iron homeostasis by enhancing iron storage and release, which may contribute to alleviating iron metabolism disorders and potentially increasing cell drug resistance." (PMID 38730240, 2024). "Moreover, FTH1-mediated iron metabolism disorder is shown to exacerbate myocardial damage during MI and reduce heart function." (PMID 34262953, 2021).
neurodegenerative disease (5 papers, 2015 to 2025). A disorder of the central nervous system characterized by gradual and progressive loss of neural tissue and neurologic function. "Despite these points, our findings support a possible link between retina and neurodegenerative diseases based on the relation between Reelin, Aβ1-42, FTH1 and TAU." (PMID 40867631, 2025).
bacterial infection (3 papers, 2018 to 2022). "For the BALF neutrophils, we observed increased Fth1 and decreased Prok2 expression in the ARDS patients compared to at-risk patients who did not develop the syndrome, including patients with bacterial infections." (PMID 36513690, 2022).
cardiovascular diseases (3 papers, 2021 to 2024). "The expression of the FTH1 gene has been associated with various diseases, including tumors, cardiovascular diseases, and neurodegenerative disorders." (PMID 38384969, 2024).
brain diseases (2 papers, 2023 to 2024). "SLC7A11 and FTH1 also play important roles in many brain diseases associated with ferroptosis." (PMID 38203455, 2023).
kidney (2 papers, 2021 to 2025). "Conditional knockdown of proximal tubule–specific FTH1 in mice worsened acute kidney injury and was associated with increased apoptosis and significant mortality." (PMID 33784251, 2021). "Similarly, in S100-induced autoimmune liver injury, upregulated ferroptosis markers (ACSL4, COX2) alongside reduced GPX4 and ferritin heavy chain (FTH1) expression correlate with disease severity." (PMID 41153801, 2025).
FTH1 also shares sentences with these, for which no sentence is quoted: cholangiocarcinoma (6 papers); Cognitive impairment (6); non-small cell lung carcinoma (6); depression (3); kidney injury (3); ovarian tumor (3); Parkinson’s (3); triple-A syndrome (3); autoimmune disease (2); fibrosarcoma (2); hematologic malignancies (2); Hyperferritinemia (2); kidney damage (2); lung squamous cell carcinoma (2); myeloid leukemia (2); Obesity (2); rhabdomyolysis (2); abortion (1); aceruloplasminemia (1); acute myocardial infarction (1); acute myocarditis (1); acute respiratory distress syndrome (1); Adrenal insufficiency (1); adrenoleukodystrophy (1); alcohol abuser (1); anaplastic astrocytoma (1); Anxiety (1); autism (1); Autoimmunity (1); brain cancer (1).
A further 70 diseases each share a sentence with FTH1 in 1 paper.